CSF1 (colony stimulating factor 1)
Diseases named in the same sentence as CSF1 in open-access papers (continued):
Sharing a sentence is not in itself a finding about the gene and the disease.
tumor (continued). "Interestingly, colony stimulating factor 1 (CSF-1) can reprogram myeloid cells, specifically into tumor-promoting macrophages in the brain parenchyma." (PMID 33466236, 2021). "In breast cancer, colon cancer, and melanoma, inhibition of CSF-1/CSF-1R signaling using an anti-CSF-1R antibody can regulate both the number and the function of MDSCs, induce antitumor T-cell responses and tumor regression when combined with CTLA-4 blockade therapy." (PMID 35003065, 2021). "These discrepancies might be attributed to the heterogenicity of different tumor species and different CSF1/CSF1R blockade agents." (PMID 34248982, 2021). "CSF-1 recruits MDSCs with the ability to support tumor immune escape by binding to CSF-1R expressed by MDSCs, and studies demonstrated that selective inhibitors PLX3397 and GW2580 could block their signaling by targeting CSF-1R." (PMID 34527668, 2021). "This may be partly due to other tumor-derived factors also attract circulating monocytes to the tumor site and differentiate into TAMs, such as CSF1, CCL5, CXCL12 and CX3CL1." (PMID 33564072, 2021). "Similarly, CSF-1 inhibitory antibodies or pharmacological inhibition of the CSF-1/CSF-1R axis effectively blocked the recruitment of macrophages at tumor sites." (PMID 34583750, 2021). "CSF1 inhibitors may further enhance the anti-tumor efficacy of BRAF inhibition in preclinical models and could also be considered." (PMID 34691054, 2021). "The TAMM was rich in CSF1-R, which could be exploited to capture the CSF1 secreted by tumor cells in the TME upon injection of UCNPs into tumor-bearing mice." (PMID 34683963, 2021). "There is also in vivo evidence suggesting that the migration of macrophages to tumors and subsequent tumor invasion are enhanced when the matrix is disrupted with either TAM-derived EGF or CSF-1 and inhibiting either of these molecules results in the opposite effect." (PMID 34202411, 2021). "Many studies on targeted therapy are based on a purposeful strategy of CSF1/CSF1R, that is, to focus on the recruitment of TAMs and the secretion of cytokines, tumor cells secrete CSF1 for the purpose of collecting TAMs by connecting CSF1 with CSF1R on macrophages." (PMID 32161718, 2020). "In addition, TAM secrete the colony-stimulating factor 1 (CSF-1) that contributes to tumor growth, invasion and metastasis in serous and mucinous EOC." (PMID 32630708, 2020). "Hence, CSF‐1–induced tumour development was an activity exactly contrary to the role of its targeting regulator, miR‐1254." (PMID 31994318, 2020). "Furthermore, tumor cell-derived CSF-1 can also enhance the maturation of those precursors to bone-resorbing osteoclasts in the presence of an osteoclastogenic milieu." (PMID 32637413, 2020). "In mesenchymal PDAC, CSF1 deactivated PSCs thereby reducing the tumor-restraining effect of PSCs." (PMID 33520728, 2020). "Pharmacological inhibition of CCL20 and CSF-1 or the genetic silencing of FOXO1 might serve as an excellent candidate to suppress tumor progression and improve prognosis." (PMID 33052231, 2020). "We found that CSF-1 expression was significantly upregulated in FOXO1(+) tumor cells." (PMID 33052231, 2020). "HCC cells play a key role in inducing the differentiation of circulating monocytes in M2 pro-tumor macrophages through the secretion of specific cytokines and growth factors, such as IL-4, IL-13, CSF-1 (Colony Stimulating Factor-1), CTGF (Connective Tissue Growth Factor)." (PMID 32164265, 2020). "Furthermore, several factors, such as macrophage-colony stimulating factor (M-CSF/CSF-1), can stimulate macrophages to promote tumor invasion." (PMID 33251232, 2020). "Furthermore, tumor cells release colony-stimulating factor 1 (CSF-1), CCL2, and CCL5, promoting the recruitment of macrophages." (PMID 33371444, 2020).
tumor (continued). "We described that CTLA-4 might regulate tumor immune microenvironment by enhancing relevant immunomodulators, such as IL-15 and CSF-1, which prime NK and M1 macrophages, two cells interconnected by their immunomodulatory functions." (PMID 32850353, 2020). "Finally, blocking the cytokine receptor for CSF1 in induced macrophages also impeded their potential to promote tumor migration and vascular mimicry in GBM cells." (PMID 32765489, 2020). "Clinical HCC samples suggested positive associations between circ-ASAP1 expression and levels of CSF-1, MAPK1, and CD68+ tumor-related-macrophages; all these could predict patient outcomes." (PMID 32665846, 2020). "IFN-α/β and IFN-γ favor tumor control, whereas TGF-β, IL-6, and CSF-1 favor tumor growth." (PMID 33297519, 2020). "Inhibition of CSF-1R by TAS-115 may suppress the polarization into M2 macrophages that depends on CSF-1 signaling, which promotes tumor growth, invasion, and metastasis, and thus, the immune environment in tumors may be improved." (PMID 31820255, 2020). "The further intravasation of the tumor cells within the blood vessel is also mediated by macrophages; inhibition of the paracrine loop between CSF-1 and EGF through silencing of epidermal growth factor receptor (EGFR) signaling results in blocked intravasation." (PMID 32477352, 2020). "Moreover, the EGF produced by tumor cells stimulated the secretion of CSF1 by cells of the microenvironment, which amplified proliferation of tumor cells." (PMID 31938054, 2020). "TAMs rely on tumor-secreted growth factors, such as CSF1, to promote tumor growth and metastasis." (PMID 33109235, 2020). "Additionally, CAIX and immunomodulatory molecules PD-L1, TGF-β, and CSF-1 were highly expressed in the tumor of the GBM-bearing mice brains." (PMID 32823915, 2020). "Finally, tumor cells produce Csf1 and IL-34 which recruit immunosuppressive Csf1r+ TAMs that produce IL-6, IL-10, and TGFβ, all factors that promote a cycle of immune suppression." (PMID 33584701, 2020). "Interestingly, colony-stimulating factor-1 (CSF1) secreted from tumor cells was shown to induce macrophages to produce epidermal growth factor (EGF), which in turn promoted the migration of cancer cells." (PMID 32986017, 2020). "Furthermore, tumours from miR‐1254 cells remarkably inhibited CSF‐1 expression, which was also confirmed by western blotting." (PMID 31994318, 2020). "Moreover, treatment with Mi-RNA-26a effectively suppressed tumor growth by downregulating colony stimulating factor-1 (CSF1 or M CSF), which further inhibited macrophage recruitment." (PMID 32899197, 2020). "Indeed, tumor cells can recruit macrophages into tumor tissues through CSF1, the main chemokine, and function regulator of macrophages." (PMID 33224886, 2020). "Therefore, targeting CSF1 or CSF1R is a promising strategy to maintain a tumor-suppressing TME with abundant collagens and activated PSCs in high-grade PDAC tumors." (PMID 33520728, 2020). "In the mid-1990s, evidence arose from CSF-1 deficient mice that the maturation and survival of macrophages had to do with cancer’s spread (i.e., metastasis), rather than cancer tumor growth." (PMID 30832375, 2019). "Consequently, ablation of TAMs by genetic depletion of CSF-1 significantly reduces the number of circulating tumor cells and diminishes metastasis." (PMID 31629410, 2019). "Additionally, several studies reveal that CSF-1 can promote tumor cell progression, migration, invasion, and metastasis." (PMID 31565097, 2019). "The inhibition of CSF-1 signaling using anti-CSF-1R neutralizing antibodies or small molecule inhibitors has been used to decrease infiltration of TAMs and MDSCs and consequently inhibit tumor progression and metastasis." (PMID 30781344, 2019). "Similarly, CSF-1 inhibition by antisense oligonucleotides or small interfering RNAs (siRNAs) suppressed tumor growth in mice xenografted with human cancer cells as a result of macrophages reduction in tumor tissues." (PMID 31370273, 2019).
tumor (continued). "The second loop is ADT-induced CSF1 expression in the tumor cells stimulates TAM infiltration." (PMID 31504033, 2019). "Therefore, targeting CSF1/CSF1R is an attractive treatment for inhibition of TAMs to suppress tumor development." (PMID 31629410, 2019). "Furthermore, the miR-1207-5p/CSF1 axis can also inhibit tumor proliferation and migration by regulating tumor microenvironment." (PMID 31380270, 2019). "Depletion of macrophages by anti-CSF1 was less efficient compared to depletion achieved by CL, which might explain why the effect of anti-CSF1 on survival and tumor growth is less pronounced compared to the CL." (PMID 31214202, 2019). "The first approach includes the elimination of TAM and monocyte accrual to the tumor site through the inhibition of mainly CSF-1/CSF-1R (Colony Stimulating Factor 1/ Colony Stimulating Factor 1 Receptor) and CCL2/CCR2 (C-C Motif Chemokine Ligand 2/ C-C Motif Chemokine Receptor 2) signaling axes." (PMID 31060337, 2019). "Furthermore, activation of autophagy in response to colony-stimulating factor-1 (CSF-1) and through AMPK signaling causes monocytes to differentiate into immunosuppressive M2-like macrophages, contributing to tumor progression." (PMID 31906065, 2019). "In addition, tumor graft models showed that CSF-1 depletion led to greatly reduced macrophage density, delayed tumor progression, and severely inhibited metastasis." (PMID 31300030, 2019). "Tumor-promoting immune cells are recruited to hypoxic regions in solid tumors owing to the secretion of chemotactic factors, such as colony stimulating factor 1 (CSF1) or vascular endothelial growth factor (VEGF), by hypoxic tumor cells." (PMID 31535086, 2019). "Although TAM numbers were significantly reduced with CSF1 blockade, they exhibited a more activated phenotype that may be due to increased inflammation within the tumor as was shown with a CSF1R inhibitor." (PMID 31552020, 2019). "Nevertheless, additional studies are needed to understand macrophage heterogeneity and function within the tumor microenvironment as well as how selective blockade of CSF1, IL34, or CSF1R and subsequent effects on TAMs correspond with response to checkpoint blockade." (PMID 31552020, 2019). "Next, we examined the CSF-1 expression for indication of correlation with different clinicopathologic characteristics including tumor stage, grade, gender, age, tumor location, tumor side, lymphovascular invasion, distant metastasis, recurrence, cancer death, and serum creatinine level." (PMID 31565097, 2019). "Cross-linking of L-selectin costimulates antigen-induced T cell proliferation and controls important effector functions such as superoxide production, colony-stimulating factor 1 release and lytic activity, all of which may contribute to tumor cell killing." (PMID 31249570, 2019). "Thus, tumor cell secretion of CSF-1 is sensed by macrophages through CSF-1R and PI3K p110α, leading to induction of the NKG2D ligand RAE-1δ." (PMID 29757143, 2018). "Here we report that the miR-125b can act through a different mechanism to control TGCT growth, as low miR-125b expression in tumor cells promotes a TAM-rich microenvironment via increasing the production of tumor-derived chemokine CSF1 and CX3CL1 for TAM recruitment." (PMID 30237497, 2018). "Thus, production of CSF-1 by tumor cells leading to activation of PI3K p110α represents a novel cellular and molecular pathway mediating NKG2D ligand expression on tumor-associated macrophages." (PMID 29757143, 2018). "Furthermore, upregulation of CSF1 by tumor cells stimulates macrophage recruitment and the production of epidermal growth factor (EGF), which in turn promotes tumor cell migration." (PMID 29594035, 2018). "CSF-1, CSF-1R, and IL-34 were weakly negatively associated with tumor purity, while the lack of association between immune cell infiltration and gene expression of PTPRZ1 and syndecan-1 was also reflected by tumor purity values." (PMID 29796177, 2018).
tumor (continued). "Furthermore, CSF-1/CSF-1R also showed a higher correlation with tumor infiltrating lymphocytes (TILs) than IL-34, PTPRZ1, and syndecan-1." (PMID 29796177, 2018). "However, after a single dose of 10 Gy to the tumours derived from both cell lines, CSF‐1 was transiently elevated." (PMID 30442705, 2018). "Once within the tumor, TAMs switch towards a M2 phenotype via colony-stimulating factor-1 (CSF-1)." (PMID 30662458, 2018). "It is interesting to speculate on other scenarios that might resemble these CSF-1-producing tumor microenvironments." (PMID 29757143, 2018). "Furthermore, the level of CSF-1 within B16 tumors was substantially greater than serum CSF-1 levels in naïve or tumor-bearing mice, consistent with previous reports describing steady-state CSF-1 levels in circulation." (PMID 29757143, 2018). "In conclusion, our study demonstrates that enforced miR-125b expression in NCCIT tumor cells can inhibit the production of tumor-derived chemokines (e.g., CSF1, CX3CL1), recruit less pro-tumorigenic macrophages to tumor sites, and ultimately suppress TGCT growth." (PMID 30237497, 2018). "As it has been shown that steady-state CSF-1 signaling is necessary for monocyte and macrophage survival in vivo, we injected tumor-bearing mice with CSF-1R antibody and monitored tumor-infiltrating macrophage numbers and RAE-1δ expression at various time points." (PMID 29757143, 2018). "CSF-1 is necessary for macrophage RAE-1δ induction by tumor conditioned media." (PMID 29757143, 2018). "Furthermore, the treatment of tumour-bearing mice with recombinant CSF-1 reestablished the tumour growth, indicating a role for macrophages in tumour growth." (PMID 29507865, 2018). "(B) Established B16 or RMA-S tumors were dissociated, and CSF-1 levels in dissociation supernatants were measured by ELISA; intra-tumoral concentrations were calculated using tumor volume measurements (total ng of CSF-1 divided by the tumor volume at time of harvest)." (PMID 29757143, 2018). "Reciprocally, tumor cells produce colony-stimulating factor 1 (CSF1) to recruit and activate TAMs." (PMID 28883015, 2017). "This phenomenon is not incomprehensible, because M1 macrophages could be induced into M2 macrophages by some tumor derived cytokines such as CSF-1, IL10 and TGF-β." (PMID 29152078, 2017). "Over expression of colony-stimulating factor 1 (CSF-1) also suggests that PVNS is a true neoplasm." (PMID 28683727, 2017). "Genetic or therapeutic targeting of the CSF‐1/CSF‐1 receptor (CSF‐1R) pathway in different tumor models leads to varying degrees of macrophage depletion; this has been found to have direct anti‐tumor activity or to potentiate the response to chemotherapy, often with anti‐angiogenic effects." (PMID 29127101, 2017). "TAMs are derived from peripheral blood monocytes and are recruited to the tumor area by various tumor-derived chemokines and cytokines such as colony stimulating factor-1 (CSF-1), C-C motif chemokine ligand 2 (CCL2), stromal cell-derived factor-1 (SDF-1), and VEGF-A." (PMID 28603525, 2017). "Tumors, which often behave like non-healing wounds, are rich in tumor-associated macrophages (TAMs), whose suppressive properties are largely regulated by colony-stimulating factor 1 (CSF1), a growth factor that is upregulated in irradiated tumors." (PMID 28348554, 2017). "Moreover, CSF-1 produced at high levels from tumor tissues promotes the differentiation of CD206+ M2 macrophages from the surviving precursors." (PMID 28686632, 2017). "The release of CSF1 may act in an autocrine manner to enhance proliferation and invasion of tumor cells." (PMID 28811522, 2017). "Finally, other combinations of ICKB and targeting the tumor microenvironment include antagonist mAbs for M-CSF/CSF1 (NCT02807844) or its receptor MCSFR/CSF1R (NCT02452424 and NCT02880371)." (PMID 28970830, 2017).
tumor (continued). "Tumor hypoxia due to a radiation-induced disruption of tumor vessels creates a transient hypoxic microenvironment and increases the expression of tumor-derived CSF-1, SDF-1 that together induces recruitment as well as anti-inflammatory activation of TAMs after radiation therapy." (PMID 28603525, 2017). "Furthermore, we discuss the local tissue macrophage and tumor-type specificities and their potential impact on CSF1/CSF1R-targeting treatment strategies for the future." (PMID 28716061, 2017). "CSF-1/CSF-1R signaling has been shown to play essential roles in regulating differentiation and survival of macrophages and driving macrophage recruitment into tumor tissues." (PMID 28424405, 2017). "Previous studies revealed the importance of CSF-1/CSF-1R expression in various tumor types." (PMID 29228668, 2017). "In addition to CSF-1 and CCL2, other chemokines have also been linked to macrophage recruitment in the primary tumor site." (PMID 26884646, 2016). "Similarly in our in vivo experiment, CSF1 inhibition delayed SUM149 tumor initiation and reduced the percentage of TAMs (F4/80+/CD206+ cells)." (PMID 27756885, 2016). "Number and size of primary tumours in CSF-1 knockout mice were similar to the control mice." (PMID 27212807, 2016). "Anti-CSF1 treated mice also exhibited reduced tumor growth, skin invasion, and local recurrence." (PMID 27756885, 2016). "In addition, tumor cells can recruit TAMs, the major inflammatory components of the tumor microenvironment by secreting the colony stimulating factor (CSF-1), the chemokine ligands 2, 3, 4, 5, and 8 (CCL2, 3, 4, 5, and 8) and VEGF." (PMID 27044404, 2016). "Inhibition of TAM recruitment after radiotherapy by neutralizing CSF-1 or blocking CSF-1R kinase activity may significantly slow tumor regrowth." (PMID 27975071, 2016). "This study provides proof-of-principal that blockade of the CSF-1/CSF-1R pathway results in fewer macrophages recruited to human breast tumors, and this change in myeloid recruitment affects the overall composition of the tumor microenvironment." (PMID 26884646, 2016). "In an in vivo study, the combined treatment of MMTV-PyMT mice with paclitaxel and anti-CSF1 antibody slowed primary tumor development, reduced development of high-grade carcinomas, and decreased pulmonary metastasis by 85% and increased CD4+ and CD8+ T-cell infiltration in primary tumors." (PMID 27756885, 2016). "After tumor irradiation, DNA damage, cell death, and increased tumor hypoxia may promote production of VEGF, SDF-1, and CSF-1, resulting in the recruitment, infiltration, and retention of monocytes/macrophages within the tumor." (PMID 27975071, 2016). "High level sM-CSF in tumor tissues accounted for the accumulation of TAMs and blockage of CSF1/CSFR signal in tumors could significantly decreased TAMs infiltration." (PMID 26595525, 2016). "CD8+ or CD103+ DCs are known to be particularly effective at crosspriming, and two recent papers report that the presence of CD103+ DCs in tumors correlates with spontaneous tumor rejection and response to treatment with paclitaxel in combination with CSF1 blockade." (PMID 26635798, 2015). "CSF-1 levels were assessed by immunohistochemistry in tumor tissues." (PMID 25886010, 2015). "Importantly, number of genes responsible tumor immune responses and desmoplastic reaction; Mst1r, TGFβr1, TGFβr2, VEGFa, CSF-1, SDF-2, CD44, IL-6ra, PD1, CD68, CD163, fibronection and MMPs were significantly reduced." (PMID 26429877, 2015). "Other possibilities to deplete macrophage populations in the developing tumor are to block differentiation of hematopoietic stem cells into macrophages by targeting colony stimulating factor 1 (CSF1) or its receptor using chemical compounds or blocking antibodies." (PMID 25897428, 2015). "Therefore, the immunosuppressive tumor milieu mediated by CSF-1 helps tumor cells escape immune responses and metastasize." (PMID 25939769, 2015).